LINC03156 (long independently transcribed non-coding RNA 3156)
Synonyms: MIR7515HG; LINC01246
Gene: Long non-coding RNA gene on chromosome 2 (6,615,389 to 6,651,104, reverse strand). Ensembl gene ENSG00000236172.
Diseases named in the same sentence as LINC03156 in open-access papers:
LINC03156 is named in the same sentence as 1 disease in open-access papers, as found by Europe PMC text mining. Sharing a sentence is not in itself a finding about the gene and the disease.
LINC03156 shares sentences with these, for which no sentence is quoted: cancer (1 paper).